AREG (amphiregulin)
Diseases named in the same sentence as AREG in open-access papers (continued):
Sharing a sentence is not in itself a finding about the gene and the disease.
tumor (continued). "However, amphiregulin and PR levels alone do not fully explain the tumor outcomes, such as in MEL mice." (PMID 31355130, 2019). "Consequently, altered expression of amphiregulin would not modify Neu-induced effects on tumor promotion and progression." (PMID 31355130, 2019). "Second, cancer cell‐autonomous AREG expression may occur in some tumor types, although not manifested by clinical samples (PCa and BCa) investigated by our study." (PMID 31493351, 2019). "AREG-targeted therapy could avoid negative side effects associated with broad EGFR inhibitors, but could also potentially direct tumor growth toward a less aggressive pattern." (PMID 30367629, 2018). "While tumour RAS status is undoubtedly a valuable predictive marker for response to EGFRIs, it remains important to investigate the roles of other potential biomarkers that could improve patient selection (e.g. epiregulin/amphiregulin, PIK3CA, PTEN)." (PMID 28424871, 2017). "The EGFR ligands: epidermal growth factor (EGF), transforming growth factor-α (TGFA), heparin-binding EGF-like growth factor (HBEGF), amphiregulin (AREG), beta-cellulin (BTC), epiregulin (EREG) and epigen (EPGN), may increase tumor growth, invasion, and metastasis through EGFR activation." (PMID 27669890, 2016). "Nevertheless we can confirm 6 of their identified genes (SPP1, TOP2A, AREG, EGR1, CD34, and IGF1) as well as one of the identified miRNAs (hsa-miR-101), that they found to be differentially expressed in lymph node metastases compared to primary tumours and to normal tissue." (PMID 26537449, 2015). "Furthermore, mIHC analysis confirmed that AREG and EGFR/ERBB2, as well as NAMPT and ITGA5/ITGB1, were overexpressed in the PMC_P region, verified in clinical specimen suggesting that these LRPs play a critical role in mediating tumor initiation in the tipping point." (PMID 40976783, 2025). "In addition, YAP/TAZ can regulate the production of secretory proteins, such as amphiregulin (AREG; an epidermal growth factor (EGF) family member), cysteine-rich angiogenic inducer 61 (CYR61), and connective tissue growth factor (CTGF), to influence the tumor microenvironment." (PMID 35701841, 2022). "In conclusion, our data suggest that while necessary, NRG1 positivity alone does not fully predict KTN3379 anti-tumor activity, but its activity was enriched in cell lines that expressed both NRG1 and high levels of AREG or TGFα." (PMID 28723928, 2017). "High mRNA levels of AREG predicted for longer survival in patients with KRAS wild-type (median survival 33 vs. 15 months, p=0.0005), but not in KRAS mutant tumours (median survival 22 vs. 17 months, p=0.64)." (PMID 23374602, 2013). "Interestingly, this survival benefit was lost with AREG knockout suggesting that, in this model, AR37 efficacy depends on tumor-derived AREG rather than immune- or stromal-derived AREG." (PMID 40727266, 2024). "In line with this study, we observed that HNSCC tumor cells expressing caveolin-1 could use EREG silencing, but not AREG silencing, to overcome oncogenic dependence on EGFR and develop resistance to CTX/irradiation combination therapy." (PMID 36899869, 2023). "Supplementation with recombinant human AREG significantly increased the formation of solid peritoneal metastases by CL31 compared to vehicle control without significantly affecting tumor cell growth rate." (PMID 33199705, 2020). "Although AREG mAb failed to generate any remarkable changes to tumor growth, combination of this antibody with MIT achieved prominent effects in abrogating tumor progression, with the efficiency approaching that manifested by combined use of MIT with a PD‐L1/PD‐1‐targeting antibody." (PMID 31493351, 2019). "Therefore it is likely, that the produced amphiregulin is provided for other cell types of the tumor stroma, which did not get in contact with HGF before or amphiregulin is provided for cell types, where the EGFR is not blocked by HGF." (PMID 25884419, 2015).
tumor (continued). "Indeed, we have established that these three inhibitors block the shedding of ADAM-17 targets such as TNFα, TGFα and amphiregulin (AREG) with the same efficacy (data not shown) whereas TMI-2 and TMI-005 only partially inhibit tumor cell growth and do not induce apoptosis." (PMID 23028451, 2012). "Co-culturing of tumour cells and fibroblasts in 3D conditions did not result in the appearance of new cytokines; rather, the amounts of certain cytokines already upregulated in 3D mono-cultures, such as GCP-2, IL-6, amphiregulin, GRO/GRO-α, IL8, and MSP-α, were further increased." (PMID 20723242, 2010).
cancer (229 papers, 2007 to 2026). A tumor composed of atypical neoplastic, often pleomorphic cells that invade other tissues. "BCAM-induced proteins, previously reported to drive EMT and associated processes such as cell migration in various cancers, include AREG, CXCL1, CXCL10, EDN1, FGF2, TGFβ1 and VEGFB." (PMID 40082910, 2025). "Abnormal expression levels of AREG in cancer cells have been associated with resistance to anti-EGFR therapy in patients." (PMID 39452130, 2024). "AREG upregulation in the cancer microenvironment has been associated with the development of many types of cancers." (PMID 39452130, 2024). "AREG, as an activating epidermal growth factor receptor ligand, is implicated in multiple cancer types and potently promotes malignant progression by promoting growth, invasion, metastasis, angiogenesis and therapeutic resistance." (PMID 36639835, 2023). "In HEK293T cells, the cancer causing tylotic iRhom2 mutant D188N enhanced amphiregulin release by oncogenic KRAS mutations." (PMID 35971826, 2022). "Several studies have also implicated AREG in ERα-mediated mammary gland development and cancer development." (PMID 31059536, 2019). "Increased AREG levels have been associated with enhanced response to EGFR TKIs in EGFR wild-type cancer cell lines and patient tumors." (PMID 27004400, 2016). "Over-expression of AREG in cancer cases is also associated with resistance to conventional chemotherapeutic agents (e.g. doxorubicin, cisplatin and sorafenib)." (PMID 27713123, 2016). "While many factors are involved in the progression of GC, aberrant expression of epidermal growth factor receptor (EGFR) and its cognate ligands (e.g. EGF and AREG) is one of the major causes for malignancy progression and cancer formation." (PMID 27713123, 2016). "As AREG expression has been associated with cisplatin resistance in many carcinoma types, we examined AREG mRNA expression in the 70 cis-/carbo-platin treated patients and compared it to five-year survival." (PMID 27669890, 2016). "This is unexpected although in many cancer cell lines with either endogenous or exogenously introduced K-ras mutation, production of erbB1 ligands, mainly TGFα and AREG, is up regulated." (PMID 23762292, 2013). "AREG levels greater than 300 pg/ml possessed a diagnostic accuracy for cancer or high-grade dysplasia of 78% (sensitivity 83%, specificity 73%)." (PMID 22333441, 2012). "Notably, T3 regulates genes associated with cancer cell invasion, including AREG, which is involved in the proliferation and branching of various tissues." (PMID 39876971, 2024). "Among these, AREG, is associated with various types of cancers and inflammatory conditions." (PMID 31835892, 2019). "Although classically thought of as epithelial specific molecules that regulate EGFR signaling via an autocrine loop, production of EREG and AREG has been detected in stromal cells including normal and cancer associated fibroblasts and various immune cell populations." (PMID 30412601, 2018). "Elevated AREG expression is associated with various pathological conditions, including cancer." (PMID 27713123, 2016). "Whereas Coffey and co-workers showed that the EGFR ligand amphiregulin is continuously released in exosomes in a signaling-competent state, leading to increased cancer cell invasion, they showed, like us, that TGFα associated with the same vesicles fraction showed no significant activity." (PMID 27264103, 2016). "Amphiregulin (AREG) has been associated with cancer cellular activities." (PMID 26503469, 2015). "Furthermore, AREG has been implicated as a paracrine/juxtacrine regulator of cell survival in other cancers and epidermal cell types." (PMID 25990246, 2015).
cancer (continued). "AREG mRNA is stabilized by m6A modification by METTL3, and the upregulation of AREG expression promotes cancer progression." (PMID 40448344, 2025). "Elevated levels of circulating AREG have been identified in multiple cancer types, suggesting its potential utility as a serum biomarker for certain malignancies." (PMID 40725192, 2025). "The therapeutic targeting of AREG aims to disrupt its pathological signaling involved in fibrosis and cancer." (PMID 40725192, 2025). "As such, targeting AREG presents a compelling alternative strategy to indirectly modulate TGF-β activity in the cancer microenvironment." (PMID 40725192, 2025). "Targeting AREG represents a promising therapeutic strategy for fibrotic diseases and cancer, particularly in contexts where EGFR-TKIs show limited efficacy." (PMID 40725192, 2025). "Therapeutic targeting of EREG and AREG has been studied in the context of several different EREG and/or AREG-expressing cancer types." (PMID 40727266, 2024). "In fact, AREG enhances proliferation and invasion of cancer cells of the breast, colon, and bladder." (PMID 38727313, 2024). "Overexpression of AREG has been documented in various human cancer tissues, including those of the head and neck, breast, lung, liver, stomach, and colon." (PMID 39451251, 2024). "While AREG plays roles in normal mammary gland growth and differentiation, its overexpression is observed in a wide variety of human cancers." (PMID 38727313, 2024). "Studies have evidenced that CREB can control AREG upregulation in immune T cells, cancer cells, and oral epithelial cells under different situations." (PMID 39452130, 2024). "The AREG protein, which is upregulated in various cancers, was present in the urine supernatant and serum of the integrated model." (PMID 38532419, 2024). "A number of SASP components including WNT16B, SFRP2, SPINK1, and AREG display strong capacity in conferring resistance to cancer cells." (PMID 37475161, 2024). "We next analyzed AREG mRNA levels in 36 pairs of PC tissues and revealed that AREG mRNA was upregulated in cancer tissues compared to normal tissues adjacent to the cancer." (PMID 37604948, 2023). "In the microenvironment, it was reported that the major sources of HGF, amphiregulin, IGF‐1, and FGF‐2 are fibroblasts, leukocyte populations, cancer‐associated fibroblasts, and epithelial/endothelial cells, respectively." (PMID 36416133, 2023). "CCL5 and AREG are critical cytokines that maintain cancer stem-like properties, such as self-renewal, the potential for nondirectional differentiation, and chemotherapy resistance." (PMID 37553567, 2023). "Some of the differentially expressed genes included cancer progression factors, such as Tff1 (trefoil factor 1), Anxa10 (annexin a10), Gnai1 (G protein subunit alpha i1), Areg (amphiregulin), and Mmp7 (matrix metalloproteinase 7)." (PMID 35703180, 2022). "AREG proteins can inhibit the growth of certain aggressive cancer cell lines and promote the growth of normal epithelial cells by interacting with EGF/TGF-α receptors." (PMID 36119517, 2022). "AREG upregulation is related to drug resistance and a failure of treatment for multiple types of cancer, including OSCCs." (PMID 35740551, 2022). "Instead, we found that release of the EGFR ligands, HB-EGF and AREG, was reduced in cocultures with ADAM17-deficient cancer cells." (PMID 35998057, 2022). "Many studies have reported that increased AREG expression stimulates cell migration and proliferation as well as reduces apoptosis in various diseases including cancers." (PMID 35732465, 2022). "Amphiregulin (AREG) is a ligand of epidermal growth factor receptor (EGFR), which is underlined to function in several aspects of cancerogenesis including cancer cell growth, invasion, metastasis, angiogenesis, and resistance to apoptosis." (PMID 36299414, 2022). "We show that ADAM17 sheds heparin-binding EGF (HB-EGF) and amphiregulin (AREG) from the cancer cell surface, leading to EGFR activation in macrophages." (PMID 35998057, 2022).
cancer (continued). "Using mass spectrometry–based proteomics and ELISA, we identified heparin-binding EGF (HB-EGF) and amphiregulin, shed by ADAM17 in the cancer cells, as the implicated molecular mediators of macrophage education." (PMID 35998057, 2022). "Genes encoding ANPEP, PROK2, CHP2, PTPRM, AREG, and COL7A1 showed significant differential expression in SRC and PC carcinomas." (PMID 35626106, 2022). "We showed that the genes encoding ANPEP, PROK2, CHP2, PTPRM, AREG, and COL7A1 were differentially expressed between SRC and PC carcinomas." (PMID 35626106, 2022). "We further screened the activated ligand-receptor pairs between ductal cells and these two stroma-cell types and defined several cancer-associated pairs, such as EGFR/TGFB1, ANXA1/FPR3, EREG/EGFR, and ICAM1/AREG." (PMID 34326696, 2021). "It is proved that the AREG mRNA levels in cancer cells was significantly correlated with the metastatic phenotype of HNSCC tissues." (PMID 35237609, 2021). "We also revealed the crosstalk between fibroblasts and cancer cells via ICAM1/AREG and collagen/integrin." (PMID 34326696, 2021). "AREG is a hallmark SASP molecule and potential biomarker, being detectable in the blood of post-treatment cancer patients." (PMID 34830209, 2021). "Amphiregulin (AREG) is an EGFR ligand, which is associated with normal tissue development and proliferation and with a wide variety of human cancers including colorectal cancer." (PMID 34893673, 2021). "EGFR in cancer cells is overexpressed, thereby activating fibroblasts and myeloid cells via several molecules such as AREG." (PMID 34326696, 2021). "Meanwhile, seven common genes, FOSL1, S100A9, CXCL12, ID2, PRS6KA3, AREG, and DUSP6, have been used as the target biomarkers and even the diagnostic tools in cancer therapy." (PMID 34490085, 2021). "Low AREG and EREG mRNA levels in mCRC tumor tissues are associated with BRAF mutations and correlated with shorter OS in patients with cancer-receiving oxaliplatin/fluoropyrimidine and bevacizumab as combinational treatment." (PMID 34884633, 2021). "Recently, another SASP factor amphiregulin (AREG) has been shown to drive cancer resistance via EFGR pathway and augment malignancy." (PMID 33855023, 2021). "In the first step, we assayed media conditioned by 14 murine cancer cell lines, and found that most lines secreted large amounts of AREG." (PMID 33941851, 2021). "Amphiregulin (AREG) is an epidermal growth factor (EGF) receptor ligand found in multiple cancer types." (PMID 34490085, 2021). "C3 activates the C3a receptor in the choroid plexus epithelium to disrupt the blood‐CSF barrier, allowing plasma amphiregulin and other mitogens to enter the CSF and promote cancer cell growth." (PMID 33377642, 2020). "Recent research supports the role of Hippo signaling in the modulation of cancer-cell proliferation and human tumorigenesis by transcriptional regulation of several cell proliferation-related genes, such as AREG, AXL, CTGF, CYR61, and VEGFA." (PMID 32365528, 2020). "MYC also induces the expression of other genes, like Adam19, Thop1, Adora2b, Hepsin, and Amphiregulin (AREG) which are then involved in cancer invasion and migration." (PMID 33081056, 2020). "The authors identified AREG as a candidate marker for sensitivity to these drugs, and knockdown of AREG gene expression inhibited cancer cell growth." (PMID 32929368, 2020). "Given the remarkable changes in cancer cell phenotypes caused by paracrine AREG, we next sought to dissect the influence of AREG on cancer cell expression pattern." (PMID 31493351, 2019). "Further, expression change of each molecule observed in cancer cells can be completely reset to their individual baseline upon elimination of AREG from stromal cells, as exemplified by the typical EMT markers." (PMID 31493351, 2019). "Targeting AREG not only minimized chemoresistance of cancer cells, but also restored immunocompetency when combined with classical chemotherapy in humanized animals." (PMID 31493351, 2019).